BPIFB6 (BPI fold containing family B member 6)
Synonyms: BPIL3; LPLUNC6
Tractability: Antibody: UniProt places it where antibodies can reach, with medium confidence; UniProt predicts a signal peptide or a membrane-spanning region; its Gene Ontology location is reachable by antibodies, with medium confidence.
Gene: Protein-coding gene on chromosome 20 (33,029,189 to 33,044,230, forward strand). Ensembl gene ENSG00000167104.
Subcellular location: Secreted
Pathways (Reactome):
Immune System: Antimicrobial peptides
Gene Ontology:
Molecular function: lipid binding
Cellular component: extracellular region
Genetic constraint (gnomAD): Loss-of-function variants: 47 observed, 56.1 expected, observed/expected ratio (o/e) 0.84, 90% interval 0.66 to 1.07. The upper end of that interval is the gene's LOEUF score, 1.07, which puts it in group 4 of 6, group 1 being the genes least tolerant of losing a copy. Missense variants: 603 observed, 589.78 expected, observed/expected ratio (o/e) 1.02, 90% interval 0.96 to 1.09. Synonymous variants: 253 observed, 238.41 expected, observed/expected ratio (o/e) 1.06, 90% interval 0.96 to 1.18.
Homologues: Orthologues: chimpanzee BPIFB6 (97% identical), macaque BPIFB6 (92% identical), pig BPIFB6 (84% identical), dog BPIFB6 (82% identical), rabbit BPIFB6 (77% identical), guinea pig BPIFB6 (77% identical), rat Bpifb6 (73% identical), mouse Bpifb6 (72% identical), Caenorhabditis elegans C06E8.5 (17% identical). Paralogues in human: BPIFB4 (29% identical), BPIFB3 (26% identical), BPI (22% identical), BPIFB2 (22% identical), LBP (21% identical), BPIFB1 (19% identical), BPIFC (18% identical), PLTP (15% identical), CETP (13% identical), BPIFA1 (9% identical), BPIFA2 (8% identical), BPIFA3 (8% identical).
Diseases named in the same sentence as BPIFB6 in open-access papers:
BPIFB6 is named in the same sentence as 1 disease in open-access papers, as found by Europe PMC text mining. Sharing a sentence is not in itself a finding about the gene and the disease. The quoted sentences say what the papers report.
bacterial infection (1 paper, 2022). "The BPIFB6, BPIFB4, BPIFB2, and BPIFB3 genes were the most significant because they are involved in biological signaling pathways, which play an essential role in innate immunity against bacterial infection." (PMID 36672756, 2022). "The BPIFB6, BPIFB4, BPIFB2, and BPIFB3 genes are the most significant because they are involved in biological signaling pathways, which play an essential role in innate immunity against bacterial infection." (PMID 36672756, 2022).